MTOR (mechanistic target of rapamycin kinase)
Diseases named in the same sentence as MTOR in open-access papers (continued):
Sharing a sentence is not in itself a finding about the gene and the disease.
uveal melanoma (continued). "In this study, we systematically evaluated gene function in laboratory models of uveal melanoma, identifying critical contributions from signaling pathways including JAK/STAT, BCL2/BCL-XL, PI3K/mTOR, and Hippo." (PMID 41514587, 2025). "Artemisinin, a natural antimalarial product, suppresses uveal melanoma cell migration and invasion ability by inactivating PI3K/AKT/mTOR, which is reverted by AKT or mTOR activators such as Sc79 and MHY1485." (PMID 36139919, 2022). "Treatment with the mTOR inhibitor rapamycin reduced HIF-1α protein levels in normal oxygen tension in OMM1 and 92.1 cells, supporting a similar paradigm in uveal melanoma cells." (PMID 25166211, 2014). "Uveal melanomas possess activation of the mitogen-activated protein kinase (MAPK) and phosphoinositide 3-kinase (PI3K)/AKT/mammalian Target of Rapamycin (mTOR) pathways." (PMID 22808163, 2012). "In this study, we explored combined MAPK and PI3K/AKT/mTOR pathway inhibition with an ATP-competitive mTOR inhibitor, AZD8055, and the allosteric MEK inhibitor, selumetinib, in uveal melanoma cell lines of various genotypic backgrounds." (PMID 22808163, 2012). "Finally, we demonstrated that G protein-mutant uveal melanomas, which are driven by YAP/TAZ, are highly dependent on mTOR-mediated translation." (PMID 39349825, 2024). "We further validated the efficacy of combining romidepsin with mTOR inhibitors in the uveal melanoma cell lines by examining the downstream mTOR pathway target S6, as well as PARP and caspase-3 cleavage after treatment with the various mTOR inhibitors in the absence or presence of romidepsin." (PMID 34533562, 2021). "Moreover, the combination of MEK1/2 inhibitors with dual PI3K/MTOR inhibitors, or PKC inhibitors, enhanced uveal melanoma cell death in a mutant GNAQ- and GNA11-dependent manner." (PMID 27057633, 2016). "The mTOR inhibitor rapamycin was able to reduce both S6 phosphorylation and HIF-1α protein levels in normoxic tumor cells, suggesting that in uveal melanoma an active mTOR cascade may promote a “hypoxic” transcriptional response even in the presence of oxygen." (PMID 25166211, 2014). "It has been hypothesized that activation of the phosphoinositide 3-kinase (PI3K)/AKT/mammalian Target of Rapamycin (mTOR) pathway cooperates with MAPK activation to generate and maintain the malignant phenotype in uveal melanomas." (PMID 22808163, 2012). "Additionally, treatment with the mTOR inhibitors alone was found to be relatively nontoxic to uveal melanoma cells, as no cleaved PARP or caspase-3 was observed." (PMID 34533562, 2021). "Therefore, we cannot definitively rule out the clinical potential of mTOR inhibition for the treatment of human uveal melanomas." (PMID 23904987, 2013). "Some in vitro models have suggested that mTOR inhibitors alone may be effective in the treatment of uveal melanoma, but others have shown that mTOR treatment alone does not result in significant amounts of apoptosis or inhibition of proliferation, suggesting a need for combination therapies." (PMID 34533562, 2021). "However, in these same conditions, LKB1 KO is able to promote uveal melanoma cell proliferation, indicating that the pro‐proliferative effect of LKB1 KO is not mediated through mTOR activation." (PMID 37966164, 2023).
diabetic retinopathy (25 papers, 2011 to 2025). "Overexpression of Wnt inhibitory factor 1 (WIF1) suppresses the Wnt/β-catenin signaling pathway, reduces the activity of the AMPK/mTOR signaling pathway, and improves the mitochondrial function caused by diabetic retinopathy." (PMID 41469379, 2025). "Formononetin has been reported to prevent retinal apoptosis via PI3K/AKT/mTOR activation and oxidative stress/NF-κB inhibition, offering therapeutic potential for diabetic retinopathy." (PMID 41573716, 2025). "In the retina, PI3K/AKT/mTOR signaling pathway is related to the early pathogenesis of diabetic retinopathy." (PMID 35669493, 2022). "Previous studies have validated the function of Meg3 related to its methylation and the PI3K/Akt/mTOR signalling pathway in diabetic retinopathy." (PMID 34717547, 2021). "This seems to run against the general consensus of inhibiting mTOR signaling pathway as a possible therapy for diabetic retinopathy." (PMID 31736682, 2019). "Novel therapeutics such as inhibitors of PI3K/Akt/mTOR pathway presents a unique opportunity for the management of diabetic retinopathy (DR)." (PMID 22132311, 2011). "The mTOR inhibitors are uniquely suited to address both early and advanced manifestations of diabetic retinopathy." (PMID 22132311, 2011). "Green Tea and epigallocatechin gallate (EGCG), both natural mTOR inhibitors, have been shown to impart protective effects in diabetic retinopathy." (PMID 22132311, 2011). "These collective observations suggest that PI3K/Akt/mTOR pathway inhibition would be suited to manage the advanced proliferative stages of diabetic retinopathy where hypoxia-driven vasoproliferative mechanisms predominate in contributing to the vasculopathy." (PMID 22132311, 2011). "Moreover, it has been reported that the inhibition of FASN impaired EC angiogenesis via mTOR malonylation in diabetic retinopathy." (PMID 37414769, 2023). "Furthermore, to our knowledge, this study was the first to demonstrate that TMZ inhibited excessive autophagy through the PI3K/Akt/mTOR pathway in an in vitromodel of diabetic retinopathy, thereby improving retinal endothelial dysfunction." (PMID 35259050, 2022). "Also, this study provides the first experimental evidence for the efficacy of mTOR activator—MHY1485 in STZ-induced diabetic retinopathy." (PMID 33637094, 2021). "We hypothesized that MMXM would block the PI3K/Akt/mTOR signaling pathway and attenuate diabetic retinopathy, thus providing a scientific basis for the treatment of DR." (PMID 33927618, 2021). "Furthermore, mTOR was found to participate in the attenuation of apoptosis by berberine in a diabetic retinopathy model in rats." (PMID 31736682, 2019). "The mTOR inhibitors could exhibit beneficial effects for diabetic retinopathy by suppressing a pro-inflammatory phenotype and modulation of redox sensitive pathways." (PMID 22132311, 2011). "Therefore, the interacted miRNAs may cause progression of T2D pathogenies regulating MAPK signaling, insulin signaling, TGF-β signaling, mTOR signaling pathways, and diabetic retinopathy signaling pathways." (PMID 38096208, 2023). "Therefore, in this study we hypothesized that TMZ could ameliorate HG-induced retinal endothelial dysfunction by inhibiting autophagy mediated by PI3K/Akt/mTOR pathway, so as to find new therapeutic drugs for diabetic retinopathy." (PMID 35259050, 2022). "Previous research has demonstrated that DNMT1 could activate the PI3K/Akt/mammalian target of rapamycin (mTOR) pathway in diabetic retinopathy)and 3,6-dihydroxyflavone (3,6-DHF), an effective DNMT1 inhibitor, suppresses the PI3K/Akt/mTOR pathway in breast carcinogenesis." (PMID 36183073, 2022). "Therefore, inhibition of PI3K/Akt/mTOR is a target for the treatment of diabetic retinopathy." (PMID 33927618, 2021).
diabetic retinopathy (continued). "The involvement of mTOR signaling in pericytes could have implications with regards to the angiogenic mechanism(s) that might be involved in pericyte biology and would be of profound relevance during early subclinical stages of diabetic retinopathy." (PMID 22132311, 2011). "During the progression of diabetic retinopathy, the expression of the mitophagy proteins PARKIN and PINK1 is upregulated, and mTOR signaling is activated." (PMID 41469379, 2025). "In diabetic retinopathy, TXNIP was reported to regulate the autophagy and apoptosis of Müller cells via the PI3K/Akt/mTOR signaling pathway." (PMID 39736512, 2024). "In diabetic retinopathy, phosphorylation of PI3K induces phosphorylation of AKT and mTOR, leading to increased expression of VEGF and the secretion of tumor necrosis factor-alpha (TNF-α) and IL-1, which accelerates the progression of diabetic retinopathy." (PMID 39595579, 2024). "In murine models of diabetic retinopathy and age‐related macular degeneration, SFN delays retinal photoreceptor cell degeneration through the Nrf2 antioxidative pathway, NF‐κB pathway, AMPK pathway, and Txnip/mTOR pathway." (PMID 39139965, 2024). "Recent advances in the research of the mammalian target of the rapamycin (mTOR) signalling pathway demonstrated that mTOR is a robust therapeutic target for ocular degenerative diseases, including age-related macular degeneration (AMD), diabetic retinopathy (DR), and glaucoma." (PMID 35883796, 2022). "No mTOR inhibitors which target the mammalian target of rapamycin are currently being clinically evaluated for their efficacy in nonproliferative or proliferative stages of diabetic retinopathy." (PMID 22132311, 2011). "The benefit to diabetic retinopathy stemming from these compounds that may be attributable to the ancillary effect of inhibition of the mTOR pathway has not been documented and remains to be elucidated." (PMID 22132311, 2011). "The results showed that TMZ inhibited excessive autophagy by activating PI3K/Akt/mTOR pathway, and reduced the permeability of cell membrane, thus improving the retinal endothelial dysfunction induced by HG, suggesting that TMZ might be a potential drug candidate for treating diabetic retinopathy." (PMID 35259050, 2022).
keloid (25 papers, 2014 to 2025). An irregularly shaped, elevated mark on the skin caused by deposits of excessive amounts of collagen during wound healing. "This review collects current knowledge on the molecular mechanisms underlying PI3K/AKT/mTOR activation in keloids and HTS, highlighting the roles of key regulators such as PTEN, NEDD4, and non-coding RNAs." (PMID 41424791, 2025). "This miR-206/mTOR axis modulation underlies the therapy’s antifibrotic efficacy in hypertrophic scars and keloids." (PMID 41424791, 2025). "KEGG pathway analysis demonstrated that these target genes were involved in the PI3K/Akt signaling pathway, mTOR signaling pathway, and cAMP signaling pathway that were all associated with the pathogenesis of keloids." (PMID 33553184, 2021). "The mammalian target of rapamycin (mTOR) has been demonstrated to be associated with keloid pathogenesis." (PMID 33062677, 2020). "In summary, the PI3K/AKT/mTOR signaling axis emerges as a central driver of the aberrant fibroproliferative response in both keloids and hypertrophic scars, orchestrating key pathogenic processes, fibroblast hyperplasia, resistance to apoptosis, excessive ECM deposition, and metabolic reprogramming." (PMID 41424791, 2025). "The PI3K/AKT/mTOR signaling pathway is deeply involved in keloid development, as it controls essential mechanisms such as fibroblast growth, collagen production, and fibrotic tissue formation." (PMID 41424791, 2025). "In this section, we review the cellular mechanisms that are affected by PI3K/Akt/mTOR in keloid formation and progression." (PMID 41424791, 2025). "Galla Chinensis ointment shows strong clinical efficacy (96.6%) against keloids by modulating the PI3K/Akt/mTOR pathway." (PMID 41424791, 2025). "Green tea extract (GTE) and its major polyphenol, EGCG, inhibit mast cell–induced collagen I production in keloid fibroblasts by suppressing the PI3K/Akt/mTOR pathway." (PMID 41424791, 2025). "Targeting PI3K/AKT/mTOR offers a compelling avenue for developing effective, mechanism-based keloid and hypertrophic scarring treatments." (PMID 41424791, 2025). "The following sections examine how various modulators regulate the PI3K/AKT/mTOR pathway during the progression of keloids and hypertrophic scars." (PMID 41424791, 2025). "Signaling pathways such as TGF-β, PI3K/Akt/mTOR, Wnt/β-catenin, and Notch play crucial roles in the occurrence and development of keloids." (PMID 40718487, 2025). "Sunitinib effectively suppresses keloid progression by inhibiting the overactive PI3K/Akt/mTOR pathway, leading to cell cycle arrest, apoptosis induction, and reduced fibroblast invasion." (PMID 41424791, 2025). "Disruption of the PI3K/AKT/mTOR pathway fosters persistent inflammation, activates fibroblasts, and drives excessive collagen deposition, hallmarks of keloid formation." (PMID 41424791, 2025). "Silibinin, a flavonoid from milk thistle with potent antifibrotic activity, inhibits keloid progression by suppressing the mTOR signaling pathway." (PMID 41424791, 2025). "P529, a dual mTORC1/2 inhibitor, effectively blocks the overactive PI3K/Akt/mTOR pathway in keloids." (PMID 41424791, 2025). "Tyrosinase inhibitors can inhibit the formation of keloids by targeting the Akt/PI3K/mTOR pathway, the MAPK/ ERK pathway." (PMID 38046417, 2023). "To confirm the increased mTOR signaling in keloid tissues, we compared the expression of p-mTOR between normal and keloid tissues using IHC." (PMID 37762688, 2023). "Several studies have demonstrated the upregulation of the mTOR signaling pathway in KFs and keloid tissues compared with normal controls." (PMID 37762688, 2023). "Semi-quantitative analysis revealed that the levels of p-mTOR increased 21.3-fold in keloid tissue compared with those in normal tissue (p < 0.01)." (PMID 37762688, 2023). "Previous study had proved that the mammalian target of rapamycin (mTOR) signaling pathway contributes to the development of keloid." (PMID 36046343, 2022).
keloid (continued). "Catechins inhibit MC-stimulated type I collagen expression by suppressing activation of the PI3k/Akt/mTOR signaling pathways in keloid fibroblasts." (PMID 33917842, 2021). "The results of qPCR showed that, compared to the control group, mRNA levels of PIK3CA, Akt1, and mTOR were significantly increased in keloid fibroblasts from the IGF-1-treated group (P < 0.05)." (PMID 33062677, 2020). "It suggests that the mechanism of Wubeizi ointment inhibiting the proliferation of keloid fibroblasts is related to the regulation of the mTOR signaling pathway." (PMID 33062677, 2020). "Immunohistochemistry, western blot, and reverse transcription-PCR were used to detect PI3K, PTEN, Akt, and mTOR in keloid tissues and keloid fibroblasts." (PMID 33062677, 2020). "Compared to the control group, the expression of p-Akt and p-mTOR significantly decreased in keloid tissues from the 3% and 5% Wubeizi ointment-treated group, and the effect was dose-dependent (P < 0.05)." (PMID 33062677, 2020). "In conclusion, the present study investigated if Wubeizi ointment inhibited the keloid formation through modulation of key molecules of the mTOR pathway including PTEN, PI3K, and Akt." (PMID 33062677, 2020). "The results of western blot showed that, compared to the control group, phosphorylated protein levels of p-PI3K, p-Akt, and p-mTOR were significantly increased in keloid fibroblasts from the IGF-1-treated group (P < 0.05)." (PMID 33062677, 2020). "This study demonstrated that Wubeizi ointment inhibited the proliferation of keloid fibroblasts and promoted the apoptosis of keloid fibroblasts, probably through downregulation of Akt and mTOR and upregulation of PTEN." (PMID 33062677, 2020). "In contrast, compared to the control group, protein levels of p-Akt and p-mTOR were significantly decreased in keloid fibroblasts from the IGF-1 + Wubeizi ointment-treated group and Wubeizi ointment-treated group (P < 0.05)." (PMID 33062677, 2020). "Tissue extracts obtained from keloid scar showed an increase in the expression of mTOR, p70KDa S6 kinase, and their activated forms, suggesting an activation of mTOR in keloid scars." (PMID 33062677, 2020). "The results of the in vivo and in vitro studies suggested that Wubeizi ointment inhibited the proliferation of keloid fibroblasts and promoted the apoptosis of keloid fibroblasts, probably through downregulation of Akt and mTOR and upregulation of PTEN." (PMID 33062677, 2020). "The mRNA levels of Akt1 and mTOR in keloid fibroblasts from the IGF-1+Wubeizi ointment-treated group was higher than those in keloid fibroblasts from the Wubeizi ointment-treated group (P < 0.05)." (PMID 33062677, 2020). "In keloid scars, the levels of endogenous mTOR, phosphorylated mTOR, and p70S6K are elevated, which exerts a symbolic effect on the activation pathway of platelet-derived growth factor (PDGF) and fibroblast growth factor 9 (FGF-9)." (PMID 32742861, 2020). "In contrast, compared to the control group, mRNA levels of Akt1 and mTOR were significantly decreased in keloid fibroblasts from the IGF-1+Wubeizi ointment-treated group and Wubeizi ointment-treated group (P < 0.05)." (PMID 33062677, 2020). "H19 is also found to enhance proliferation ability of keloid fibroblasts through the regulation of mammalian target of rapamycin (mTOR) and vascular endothelial growth factor." (PMID 30458806, 2018). "It has been shown that GTCs significantly inhibit mast cell stimulated type I collagen expression by suppressing activation of the PI-3k/Akt/mTOR signalling pathways in keloid fibroblast culture." (PMID 27086034, 2016). "Although other reports have found that mTOR is activated in Cav-1 knock out CAFs and keloids, the newly identified axis in CAFs (Cav-1 to mTOR to RB) requires further clarification." (PMID 25202343, 2014). "Different treatments targeting PI3K/AKT/mTOR in hypertrophic scars and keloids." (PMID 41424791, 2025).